TNF (tumor necrosis factor)
Diseases named in the same sentence as TNF in open-access papers (continued):
Sharing a sentence is not in itself a finding about the gene and the disease.
trachoma (8 papers, 2008 to 2023). "For example, poor facial cleanliness and presence of flies are risk factors for active trachoma, while genetic polymorphisms in TNF-α, IFNγ, IL-10, IL8, and CSF2 have been linked to risk of trachomatous scarring." (PMID 37287960, 2023). "Likewise, polymorphisms in the TNF locus are linked with an increased risk of severe inflammatory sequelae in blinding trachoma and PID13–15." (PMID 34526512, 2021). "We and others found elevated TNFα levels among TI and chronic trachoma cases and also higher levels when both C. trachomatis infection and trachoma were present." (PMID 18628987, 2008). "Notably, polymorphisms in TNF-α and NLRP3 inflammasome pathway genes were linked to disease severity of trachoma and PID13–16 suggesting a role of innate immunity in immunopathology." (PMID 34526512, 2021). "In trachoma, the prolonged production of TNFα and IL-β together with a reduction in IL-1Ra inhibitory pathways may promote the development of scarring and progression to TT." (PMID 18628987, 2008). "We found that proinflammatory cytokines IL-1β (r = 0.259, P = 0.001) and TNFα (r = 0.168, P<0.05) were significantly associated with trachomatous disease and concurrent C. trachomatis infection compared with age and sex matched controls from the same region who did not have trachoma." (PMID 18628987, 2008). "Similarly, this immunosuppressive polarized environment was mirrored in infected TS cases where conjunctival IFNγ, TNFα, and IL-12 mRNA expression levels were decreased compared to levels among TF/TI cases, although IL-1β and TGFβ1 levels were consistently elevated for all grades of trachoma." (PMID 18628987, 2008).
transient cerebral ischemia (8 papers, 2010 to 2025). "Inhibition of TNF-α reduced the brain infarct volume and suppressed the inflammatory responses in a mouse model of transient cerebral ischemia." (PMID 24348730, 2013). "At 24 h after transient cerebral ischemia (2 h ischemia/reperfusion), JQ1-treated rats exhibit a marked reduction in neurological deficits, infarct volume, and expression of pro-inflammatory mediators IL-1β, IL-6, IL-17, and TNF-α in the ischemic brain." (PMID 34604312, 2021). "After transient cerebral ischemia injury (1 h ischemia and 3 days of reperfusion), JQ1 significantly reduces infarct volume, neurological deficit score, and glial activation in ischemic mice, along with significantly decreased levels of pro-inflammatory factors IL-1β, IL-6, IL-18, and TNF-α." (PMID 34604312, 2021).
trigeminal neuralgia (8 papers, 2016 to 2025). Trigeminal neuralgia is a nerve disorder that causes a stabbing or electric-shock-like pain in parts of the face. "It indicates that TNF-α causes the potential trigeminal neuralgia associated with thermal (chemical) sensation in trigeminal nerve endings." (PMID 40728987, 2025). "It indicates that TNF-α causes the potential trigeminal neuralgia associated with the biomarker changes in the trigeminal nerve." (PMID 40728987, 2025). "Our present data also proved that endoneural injection of TNF-α causes potential trigeminal neuralgia." (PMID 40728987, 2025). "It indicates that TNF-α causes the potential trigeminal neuralgia associated with mechanical sensation in trigeminal nerve endings." (PMID 40728987, 2025). "In the present study, biomarkers and histological assessment revealed the same results in TNF-α-induced trigeminal neuralgia in rats." (PMID 40728987, 2025). "The oral administration of DMC (100 and 200 mg/kg; p.o. for 10 consecutive days) attenuates the TNF-α-induced trigeminal neuralgia in a dose and time-dependent manner when compared to the TNF-α-administered group." (PMID 40728987, 2025). "Hence, the present study is designed to investigate the therapeutic potential of DMC in TNF-α-induced trigeminal neuralgia in rats." (PMID 40728987, 2025). "In a trigeminal neuralgia model established by trigeminal nerve root compression, BoNT/A administration reduced levels of inflammatory cytokines in TG, specifically IL-1β, IL-6, and TNF-α." (PMID 41441603, 2025). "In addition, certain pro-inflammatory cytokines, like TNF-a, IL-17, and IL-6, were also found to be elevated in the saliva of trigeminal neuralgia patients compared to controls." (PMID 35237471, 2022). "Hence, DMC may have potential for use for the trigeminal neuralgia due to its potential antioxidant, anti-inflammatory, and anti-TNF-α actions." (PMID 40728987, 2025). "Thus, targeting the CXCL13/CXCR5/ERK/TNF-α and IL-1β pathway in the TG may provide a novel therapeutic approach for the treatment of the trigeminal neuralgia." (PMID 27401148, 2016). "In the present study patients with trigeminal neuralgia showed lower levels of growth factor levels such as Ang-2, bFGF, HGF, SCF, TGF-α, and VEGF and higher cytokine levels of IL-1β, TNF-α, CCL2, IL-17A, IL-6, and CXCL8 in comparison with normal individuals." (PMID 34067581, 2021). "In this study, we established a new animal model of trigeminal neuralgia and investigated the role of P2X3 receptor (P2X3R) alteration in the trigeminal ganglion (TG) via tumor necrosis factor alpha (TNFα) signaling in persistent orofacial pain." (PMID 33902429, 2021). "In view of recent reports of significant up-regulation of TNF-α and IL-6 in trigeminal ganglion in rodent models of trigeminal neuralgia, it would be interesting to study the trigeminal nociception in PD mice challenged with Aa EVs." (PMID 37871107, 2023). "Similarly, in a lysophosphatidic acid (LPA)-induced trigeminal neuralgia model, a subcutaneous injection of BoNT/A into the whisker pad downregulated the expression of NLRP3, and well-known inflammatory cytokines IL-1β, IL-18, and tumor necrosis factor (TNF)-α." (PMID 41441603, 2025).
tularemia (8 papers, 2011 to 2023). Tularemia is an infection caused by the bacterium Francisella tularensis. "However, TNF-/-, IL-6-/- and Casp1/11-/- mice are more susceptible to pulmonary tularemia and, demonstrating the essential role of these cytokines in tularemia." (PMID 27015566, 2016). "Mouse knockout models have demonstrated critical roles for IFN-γ and TNF-α in the immune response against Ft as knockout mice succumb to tularemia more rapidly than wildtype mice." (PMID 34202420, 2021). "Later in pulmonary tularemia, the release of inflammatory cytokines (IL-1β, IL-6, TNFα, etc.)and DAMPs/alarmins (e.g. HMGB1, S100A9) are suggested ‘drivers’ of host death." (PMID 27015566, 2016). "Specifically, IL-2, MIP-1β, TNF, and IL-7 all fulfilled the criterion and the former three of these cytokines have previously been observed to correlate the control of infection in a human co-culture model and also in an animal models of tularemia." (PMID 37781364, 2023). "To gain mechanistic insight into exactly what drives the hypercytokinemia observed during late-phase tularemia, we evaluated whether the damaged mitochondria isolated from infected lung tissue could elicit proinflammatory cytokines (that is, TNF)." (PMID 28955505, 2017). "As TNF-α is protective against tularemia, it is possible that nasal administration of Acai PS also has an effect against systemic replication of Francisella, which may account for the post-exposure protection conferred by Acai PS observed here." (PMID 22438809, 2012). "GSK3 inhibition reduced IL-12p40, IL-6 and TNF-α in a mouse model of tularemia." (PMID 21483672, 2011). "Thus, there is substantial indirect evidence that levels of Th1 cytokines, such as IFN-γ, TNF, and MIP-1β, are correlates of protection in various animal and human tularemia models, thereby in much agreement with the present findings." (PMID 37781364, 2023). "What is yet to be fully explained is how this mode of programmed HCD is initiated in the absence of TNF production or TNFR1 stimulation during the early phase (<72 h) of tularemia." (PMID 28955505, 2017). "Host cell recognition of and response to released mitochondria and other damage-associated molecular patterns engenders a sepsis-like syndrome typified by production of TNF, IL-1β, IL-6, IL-12p70, and IFN-γ during late-phase tularemia (⩾72 h), but are absent early during infection." (PMID 28955505, 2017).
vaginal infection (8 papers, 2016 to 2025). "In this study, the inflammatory profile was assessed by measuring levels of four pro-inflammatory cytokines, IL-6, IL-1β, TNF-α, and IL-8, known to be associated with inflammatory processes linked to vaginal infections." (PMID 38337685, 2024). "In the presence of vaginal infection, TNF-α decreased among CIN 1+ participants while IL-10 remained elevated." (PMID 37635942, 2023). "Similarly, cox-2 is an enzyme related to pro-inflammatory responses that can be induced in human cervico-vaginal cells as a response to toll-like receptor (TLR)-ligands and TNF-α, as demonstrated in an in vitro model of vaginal infection." (PMID 27614611, 2016). "The second of these was assessed with a multi-analyte flow assay kit to determine the levels of IL-6, TNF-α, IL-1β, IL-10, IL-1α, IL-17a, MCP-1, and IFN-γ in the supernatant of cervical tissue homogenate of GrpE-immunized mice and control groups after vaginal infection." (PMID 32849509, 2020).
arteritis (7 papers, 2013 to 2025). An inflammatory process affecting an artery. "The extent of arteritis correlated with the plasma TNF-α levels, suggesting a pivotal role of TNF-α in KD." (PMID 23606968, 2013). "We found that etanercept, an anti-TNF agent, was most effective in attenuating the arteritis by reducing cytokine levels compared to the other drugs studied." (PMID 23606968, 2013). "T lymphocyte activation, antigen presentation, immunoglobulin production, and type I interferon response were significantly upregulated in KD arteritis, while the tumor necrosis factor α pathway was not differentially expressed." (PMID 26679344, 2015).
Arthralgia (7 papers, 2009 to 2025). "Thus, it is possible that CHIKV-induced arthralgia does not depend on TNF-α." (PMID 19156204, 2009).
Brain atrophy (7 papers, 2019 to 2026). Partial or complete wasting (loss) of brain tissue that was once present. "A relevant study revealed that plasma levels of peripheral inflammatory markers, such as BAFF/TNFSF13B, IL-4, IL-6, IL-17A, and TNF-α, exhibited associations with patterns of brain atrophy, brain hypometabolism, and clinical measures of disease severity and functional status in bvFTD." (PMID 37762113, 2023).
breast invasive carcinoma (7 papers, 1998 to 2024). "We found that the gene expression of TAF7 and TNF is induced upon tumorigenesis and more greatly overexpressed in response to the metastatic level of breast invasive carcinoma." (PMID 39457533, 2024). "We have also shown that TAMs are a major source of TNF-alpha in invasive breast carcinomas, and that macrophage-like stromal cells as well as tumour cells synthesize TP in such tumours." (PMID 9649140, 1998). "In addition, we performed a differential gene expression analysis of TAF7 and TNF using RNA-Seq-based data from testicular germ cell tumors and breast invasive carcinoma." (PMID 39457533, 2024). "To do this, we used a cocktail of non-neutralizing monoclonal anti-TNF-alpha antibodies to visualize both TNF-alpha-expressing macrophages and TNF-alpha bound to its receptors on tumour cells and endothelial cells in a series of 93 invasive carcinomas of the breast." (PMID 9649140, 1998). "T-cell infiltration in invasive breast cancer has been reported that secrete several inflammatory cytokines, for example interferon-γ (IFNγ), transforming growth factor beta (TGF-β), tumor necrosis factor alpha (TNFα) and interleukin-2 (IL-2)." (PMID 32533334, 2020).
C. perfringens infection (7 papers, 2018 to 2025). "Compared to the CON group, C. perfringens infection significantly elevated serum levels of IL-1β, IL-6, and TNF-α, while suppressing IL-4 and IL-10 (p < 0.05)." (PMID 40427288, 2025). "In line with earlier findings in piglets and IPEC-J2 cells, we observed that C. perfringens infection significantly increased the serum levels of IL-1β, IL-6, and TNF-α, while decreasing those of IL-4 and IL-10." (PMID 40427288, 2025). "High and Medium dose C. perfringens infection significantly increased (P < 0.05) the concentration of IL-1β, IL-6, and TNF-α compared with Control group." (PMID 35769317, 2022). "Similar results were obtained in the current study, where C. butyricum was found to increase the expression of TNF in response to C. perfringens infection." (PMID 31681193, 2019). "Compared with the other three groups, C. perfringens infection induced the highest expression of TNF in the CB/CP group." (PMID 31681193, 2019). "Unlike LPS, there was a lower production of TNF-α and IL-6 response to C. perfringens infection under HKCA training compared with the control group." (PMID 38622656, 2024). "Although HKCA-trained PM produced decreased levels of TNF-α and IL-6, the importance of trained immunity was demonstrated by the fact that HKCA training resulted in enhanced bacterial phagocytic ability and clearance in vivo and in vitro during C. perfringens infection." (PMID 38622656, 2024).
cardiopulmonary disease (7 papers, 2005 to 2025). "The purpose of this study was to explore the pharmacological effects of HGWD in treating joint inflammation in TNF-Tg mice and its complicated cardiopulmonary diseases." (PMID 35600883, 2022). "Hindpaw micro-CT was performed on wild-type (n = 4 male, n = 4 female) and TNF-Tg (n = 4 male, n = 7 female) mice at monthly intervals from 2–5 (females) and 2-8-months (males) of age, since female TNF-Tg mice exhibit early mortality from cardiopulmonary disease at approximately 5-6-months." (PMID 38968295, 2024).
cervical tumor (7 papers, 2008 to 2025). "The cervical tumor microenvironment is rich in pro-inflammatory cytokines such as interleukin-6 (IL-6), tumor necrosis factor-alpha (TNF-α), and interferon-gamma (IFN-γ), which interfere with iron metabolism and erythropoiesis." (PMID 40901092, 2025). "CaSki human cervical tumor cells were exposed to TNF-α 10 ng/mL and TGF-β1 alone or in combination for 5 days." (PMID 37445768, 2023). "In the present study, we investigated its anti-inflammatory effect on the interleukin-1β (IL-1β), tumor necrosis factor-α (TNF-α), and PMNs activity in a methylcholanthrene- (MCA-) induced uterine cervix tumorigenesis murine model system." (PMID 25874230, 2015). "Furthermore, it may provide insights of the molecular mechanisms of HPV-induced TNF resistance, contribute to the identification of key functions and pathways associated to specific HPV types and, finally, lead to the identification of new cervical tumor progression markers." (PMID 18588690, 2008).
chronic granulomatous disease (7 papers, 2010 to 2025). Chronic granulomatous disease (CGD) is a rare primary immunodeficiency, mainly affecting phagocytes, which is characterized by an increased susceptibility to severe and recurrent bacterial and fungal infections, along with the development of granulomas. "PMNs from chronic granulomatous disease (CGD) patients (NADPH oxidase-deficient) or PMNs treated with DPI (NADPH oxidase inhibitor) exhibit delayed apoptosis in the presence of TNF-α and bacteria." (PMID 20174624, 2010). "In a model of murine chronic granulomatous disease pioglitazone increased TGFβ and IL-10 while decreasing KC (mouse homologue to IL-8), IL-6, and TNFα expression." (PMID 26713087, 2015). "Reports have shown individuals with HIV, transplantation, common variable immunodeficiency (CVID), chronic granulomatous disease (CGD), or on treatment with tumor necrosis factor (TNF) inhibitors, steroids, bisphosphonates, radiotherapy, and chemotherapy are susceptible to actinomyces infection." (PMID 41170249, 2025). "Such an hypothesis gains support from published data; cells from mice deficient in MPO produce increased levels of cytokines including TNFα, as do cells that cannot produce NADPH-oxidase-derived ROS, isolated from patients suffering from chronic granulomatous diseases (CGD)." (PMID 37954595, 2023).
coccidiosis (7 papers, 2018 to 2024). A parasitic infection caused by Coccidia. "The SC chickens treated with an antibody against TNF showed less body weight loss during E. tenella infection, indicating the involvement of TNF in coccidiosis pathogenesis." (PMID 35214673, 2022). "Generally, cytokines such as IL-1β, IL-12, IFN-γ, and TNF-α promote the development of cellular-mediated immunity against intracellular infections including coccidiosis." (PMID 38751432, 2024). "In coccidiosis, there is increased synthesis of proinflammatory cytokines such as IL-1β, IL-6, and TNF-α, which further disrupt the TJ barrier and amplify the inflammatory process by allowing more luminal antigens to permeate." (PMID 37763330, 2023). "involves intracellular (asexual), and extracellular (sexual) phases, a severe immune response mediated by NF-κβ activation results in the release of IFN-γ and TNF-α that contribute to the pathophysiology of coccidiosis in chickens." (PMID 30186844, 2018). "The role of TNF in coccidiosis has been investigated in chickens." (PMID 35214673, 2022). "TNF-α leads to the development of a protective immunity on the one hand, but, on the other hand, it participates in the pathogenesis of coccidiosis, because treatment of chickens with antibodies against TNF-α results in a partial abrogation of E. tenella-induced body weight loss in chickens." (PMID 29699573, 2018).
corneal diseases (7 papers, 2015 to 2024). "Disruption of the epithelium has been shown to promote ocular inflammation in corneal disorders via the upregulation and abnormal secretion of proinflammatory cytokines interleukin (IL)-1β/6 and tumor necrosis factor-α (TNF-α)." (PMID 37544647, 2023). "Antibody based biologics with specificity for tumor necrosis factor-alpha (TNFα) are also currently examined for efficacy in modulating corneal disease in experimental animals." (PMID 26664467, 2015). "TNF-α is a proinflammatory mediator that plays an important role in a variety of corneal diseases." (PMID 31003493, 2019). "Pretreatment with fucoxanthin may protect against UVB radiation-induced corneal disorders by inhibiting expression of proinflammatory factors, TNF-α, and VEGF and by blocking polymorphonuclear leukocyte infiltration." (PMID 26751458, 2016).
cryopyrin-associated periodic syndrome (7 papers, 2018 to 2024). Cryopyrin associated periodic syndrome (CAPS) defines a group of autoinflammatory diseases, characterized by recurrent episodes of systemic inflammatory attacks in the absence of infection or autoimmune disease. "There are currently several Food and Drug Administration (FDA) approved TNF-α, IL-1 and IL-6 inhibitors for clinical indications such as rheumatic diseases, Crohn's disease and cryopyrin-associated periodic syndromes (CAPS)." (PMID 33050789, 2020).